DDI1 (DDI proteasomal shuttling factor 1)
Description:
Probable aspartic protease (Probable). Seems to act as a proteasomal shuttle which links the proteasome and replication fork proteins like RTF2 (Probable). Required, with DDI2, for cellular survival following replication stress. Together or redundantly with DDI2, removes RTF2 from stalled forks to allow cell cycle progression after replication stress and maintains genome integrity.
Synonyms: FLJ36017
Tractability: PROTAC: ubiquitination databases record sites on it.
Gene: Protein-coding gene on chromosome 11 (104,036,640 to 104,039,196, forward strand). Ensembl gene ENSG00000170967.
Gene Ontology:
Molecular function: protein binding; aspartic-type endopeptidase activity
Biological process: cellular response to hydroxyurea; proteasomal protein catabolic process; regulation of DNA stability; regulation of protein stability; proteolysis
Cellular component: cytoplasm
Genetic constraint (gnomAD): Loss-of-function variants: 14 observed, 16.37 expected, observed/expected ratio (o/e) 0.86, 90% interval 0.56 to 1.34. The upper end of that interval is the gene's LOEUF score, 1.34, which puts it in group 5 of 6, group 1 being the genes least tolerant of losing a copy. Missense variants: 502 observed, 546.26 expected, observed/expected ratio (o/e) 0.92, 90% interval 0.85 to 0.99. Synonymous variants: 221 observed, 214.67 expected, observed/expected ratio (o/e) 1.03, 90% interval 0.92 to 1.15.
Homologues: Orthologues: macaque DDI1 (96% identical), rabbit DDI1 (85% identical), pig DDI1 (84% identical), dog DDI1 (83% identical), rat Ddi1 (83% identical), mouse Ddi1 (81% identical), guinea pig DDI1 (81% identical), tropical clawed frog ddi2 (68% identical), zebrafish ddi2 (68% identical), Drosophila melanogaster rngo (48% identical), Caenorhabditis elegans ddi-1 (28% identical). Paralogues in human: DDI2 (71% identical), NRIP3 (13% identical), NRIP2 (12% identical), UBAC2 (12% identical).
Diseases named in the same sentence as DDI1 in open-access papers:
DDI1 is named in the same sentence as 8 diseases in open-access papers, as found by Europe PMC text mining. Sharing a sentence is not in itself a finding about the gene and the disease. The quoted sentences say what the papers report.
Angelman syndrome (2 papers, 2019). A neurogenetic disorder characterized by severe intellectual deficit and distinct facial dysmorphic features. "For that reason, among the six DDI1 ubiquitination sites detected in the present study, our interest focused on the ones mediated by UBE3A, as it is likely that UBE3A-dependent ubiquitination events are altered in Angelman syndrome patients." (PMID 31130875, 2019). "Emerging evidence is suggesting that Ddi1 has biological functions not yet described that may be of relevance for clinical research on Angelman syndrome." (PMID 30999567, 2019).
malaria (1 paper, 2018). Malaria is a serious and sometimes fatal disease caused by a parasite that commonly infects a certain type of mosquito which feeds on humans. "Here, we show the in silico binding profiles of LP and SQ on the Ddi1 protein and provide evidence that the retropepsin-like protease is essential for the asexual stage of the malaria parasite." (PMID 30067811, 2018). "Future work tailored towards understanding the functions of Ddi1 in Plasmodium parasites and its candidature as a target for drugs may inform the development of future drugs against the malaria parasite." (PMID 30067811, 2018). "We then reasoned that since deletion of the Ddi1 seemed toxic to the growth of the asexual blood stage parasites, the protein might have unique and conserved motifs across the different malaria parasites." (PMID 30067811, 2018). "Using the rodent malaria parasite, P. berghei, and highly efficient PlasmoGEM genetic modification vectors, we engineered the Plasmodium aspartyl proteases; PM4, PM7, PM8 and Ddi1 in our quest to understand the possible mechanisms of action of LP and SQ (the most active RPIs)." (PMID 30067811, 2018).
neuroblastoma (1 paper, 2019). Neuroblastoma (NB) is the most common solid, extracranial childhood tumor. "We recently discovered that Ube3a ubiquitinates endogenous Rngo in flies, and also its human homolog DDI1 when transfected in S5-SYHY neuroblastoma cells." (PMID 31130875, 2019). "The proteasome receptor DDI1 has been identified both in Drosophila photoreceptor neurons and in human neuroblastoma cells in culture as a direct substrate of UBE3A." (PMID 31130875, 2019).
cancer (2 papers, 2008 to 2016). A tumor composed of atypical neoplastic, often pleomorphic cells that invade other tissues. "Targeting mammalian DDI1 protease could mitigate effects of proteasome dysfunction in aging and protein aggregation disorders, or increase effectiveness of proteasome inhibitor cancer chemotherapies." (PMID 27528192, 2016). "These include a number of known or potential tumour suppressor genes (BCSC-1, CHEK1, ST14, ATM, P53AIP1), genes with proposed roles in cancer progression (BARX2), apoptosis (PIG8, P53AIP1) and oncogenesis (FLI1, ETS1), and a DNA damage-inducible gene (DDI1)." (PMID 18506147, 2008).
infection (1 paper, 2018). The state of being infected such as from the introduction of a foreign agent such as serum, vaccine, antigenic substance or organism. "Three successive attempts to delete the Ddi1 failed to recover parasite twenty days post infection suggesting that the Ddi1 gene was refractory to deletion and thus essential for the asexual blood stage parasite growth." (PMID 30067811, 2018).
DDI1 also shares sentences with these, for which no sentence is quoted: tumor (2 papers); bacterial infection (1); multiple myeloma (1).